MIR130A (microRNA 130a)
Synonyms: hsa-mir-130a; MIRN130A; miRNA130A; mir-130a
Gene: MicroRNA gene on chromosome 11 (57,641,198 to 57,641,286, forward strand). Ensembl gene ENSG00000208009.
Gene Ontology:
Biological process: miRNA-mediated post-transcriptional gene silencing
Cellular component: RISC complex
Homologues: Orthologues: chimpanzee ptr-mir-130a (100% identical), macaque mml-mir-130a (100% identical), pig ssc-mir-130a (83% identical), dog MIR130A (70% identical), guinea pig MIR130A (67% identical), tropical clawed frog xtr-mir-130a (66% identical), mouse Mir130a (65% identical), zebrafish mir130a-2 (65% identical), zebrafish mir130c-2 (64% identical), zebrafish mir130c-1 (63% identical), tropical clawed frog xtr-mir-130c (58% identical). Paralogues in human: MIR301A (52% identical), MIR301B (46% identical).
Diseases named in the same sentence as MIR130A in open-access papers:
MIR130A is named in the same sentence as 3 diseases in open-access papers, as found by Europe PMC text mining. Sharing a sentence is not in itself a finding about the gene and the disease. The quoted sentences say what the papers report.
thyroid cancer (1 paper, 2019). "Further, MIR130A could inhibit NKX2-5 to reduce cancer cell proliferation, migration and dedifferentiation, but it is significantly downregulated in thyroid cancer cells." (PMID 31126066, 2019).
cancer (1 paper, 2019). A tumor composed of atypical neoplastic, often pleomorphic cells that invade other tissues. "MIR130A, which could inhibit the gene NKX2-5, could act as a miRNA of tumor-inhibiting to inhibit cancer cell proliferation, migration and dedifferentiation." (PMID 31126066, 2019).
MIR130A also shares sentences with these, for which no sentence is quoted: tumor (1 paper).